RTN4 (reticulon 4)
Description:
Required to induce the formation and stabilization of endoplasmic reticulum (ER) tubules. They regulate membrane morphogenesis in the ER by promoting tubular ER production. They influence nuclear envelope expansion, nuclear pore complex formation and proper localization of inner nuclear membrane proteins. However each isoform have specific functions mainly depending on their tissue expression specificities (Probable). [Isoform A]: Developmental neurite growth regulatory factor with a role as a negative regulator of axon-axon adhesion and growth, and as a facilitator of neurite branching. Regulates neurite fasciculation, branching and extension in the developing nervous system. Involved in down-regulation of growth, stabilization of wiring and restriction of plasticity in the adult CNS. Regulates the radial migration of cortical neurons via an RTN4R-LINGO1 containing receptor complex (By similarity). Acts as a negative regulator of central nervous system angiogenesis. Inhibits spreading, migration and sprouting of primary brain microvascular endothelial cells (MVECs). Also induces the retraction of MVECs lamellipodia and filopodia in a ROCK pathway-dependent manner (By similarity). [Isoform B]: Mainly function in endothelial cells and vascular smooth muscle cells, is also involved in immune system regulation (Probable). Modulator of vascular remodeling, promotes the migration of endothelial cells but inhibits the migration of vascular smooth muscle cells. Regulates endothelial sphingolipid biosynthesis with direct effects on vascular function and blood pressure. Inhibits serine palmitoyltransferase, SPTLC1, the rate-limiting enzyme of the novo sphingolipid biosynthetic pathway, thereby controlling production of endothelial sphingosine-1-phosphate (S1P). Required to promote macrophage homing and functions such as cytokine/chemokine gene expression involved in angiogenesis, arteriogenesis and tissue repair. Mediates ICAM1 induced transendothelial migration of leukocytes such as monocytes and neutrophils and acute inflammation. Necessary for immune responses triggered by nucleic acid sensing TLRs, such as TLR9, is required for proper TLR9 location to endolysosomes. Also involved in immune response to LPS. Plays a role in liver regeneration through the modulation of hepatocytes proliferation (By similarity). Reduces the anti-apoptotic activity of Bcl-xl and Bcl-2. This is likely consecutive to their change in subcellular location, from the mitochondria to the endoplasmic reticulum, after binding and sequestration. With isoform C, inhibits BACE1 activity and amyloid precursor protein processing. [Isoform C]: Regulates cardiomyocyte apoptosis upon hypoxic conditions (By similarity). With isoform B, inhibits BACE1 activity and amyloid precursor protein processing.
Synonyms: NSP; KIAA0886; NOGO; NSP-CL; ASY; NOGOA; NOGOB; NOGOC; NI220/250; Nbla00271; Nbla10545; RTN-X; RTN4-A; RTN4-B1; RTN4-B2; RTN4-C
Tractability: Antibody: a drug acting on it is in phase 2 or 3 trials; UniProt places it where antibodies can reach, with high confidence; its Gene Ontology location is reachable by antibodies, with high confidence; UniProt predicts a signal peptide or a membrane-spanning region. PROTAC: ubiquitination databases record sites on it; its protein half-life has been measured.
Gene: Protein-coding gene on chromosome 2 (54,972,187 to 55,112,621, reverse strand). Ensembl gene ENSG00000115310.
Subcellular location: Endoplasmic reticulum membrane (Isoform A); Cell membrane; Synapse; Endoplasmic reticulum membrane (Isoform B); Cell junction; Endoplasmic reticulum membrane (Isoform C)
Subcellular location (Human Protein Atlas): Endoplasmic reticulum
Pathways (Reactome):
Signal Transduction: Axonal growth inhibition (RHOA activation)
Gene Ontology:
Molecular function: cadherin binding; protein binding; RNA binding; ubiquitin protein ligase binding
Biological process: endoplasmic reticulum tubular network formation; endoplasmic reticulum tubular network membrane organization; endoplasmic reticulum tubular network organization; negative regulation of amyloid-beta formation; negative regulation of axon extension; negative regulation of cell growth; nuclear pore complex assembly; positive regulation of epithelial cell migration; positive regulation of ERBB3 signaling pathway; positive regulation of mammary gland epithelial cell proliferation; positive regulation of phosphatidylinositol 3-kinase/protein kinase B signal transduction; positive regulation of protein localization to endoplasmic reticulum; protein stabilization; apoptotic process; axonal fasciculation; brain development; cerebral cortex radial glia-guided migration; neuron differentiation; positive regulation of toll-like receptor 9 signaling pathway; protein localization to lysosome; regulation of apoptotic process; regulation of branching morphogenesis of a nerve; intracellular sphingolipid homeostasis; modulation of chemical synaptic transmission; regulation of nervous system development; and 1 more
Cellular component: anchoring junction; endoplasmic reticulum; endoplasmic reticulum membrane; endoplasmic reticulum tubular network; endoplasmic reticulum tubular network membrane; nuclear envelope; plasma membrane; neuron projection; postsynaptic density; synapse; glutamatergic synapse; neuronal cell body; postsynapse
Genetic constraint (gnomAD): Loss-of-function variants: 31 observed, 76.63 expected, observed/expected ratio (o/e) 0.4, 90% interval 0.3 to 0.55. The synonymous counts are far from expectation, so gnomAD's model fits this gene poorly and the ratio says little. Missense variants: 1,628 observed, 1,318.8 expected, observed/expected ratio (o/e) 1.23, 90% interval 1.18 to 1.29. Synonymous variants: 610 observed, 508.84 expected, observed/expected ratio (o/e) 1.2, 90% interval 1.12 to 1.28.
Homologues: Orthologues: chimpanzee RTN4 (98% identical), macaque RTN4 (96% identical), dog RTN4 (85% identical), pig RTN4 (83% identical), rat Rtn4 (76% identical), mouse Rtn4 (75% identical), rabbit RTN4 (73% identical), tropical clawed frog rtn4 (38% identical), Drosophila melanogaster Rtnl1 (13% identical), zebrafish rtn4a (13% identical), Drosophila melanogaster Rtnl2 (6% identical). Paralogues in human: RTN1 (20% identical), RTN3 (18% identical), RTN2 (12% identical), PRR18 (3% identical).
Diseases named in the same sentence as RTN4 in open-access papers:
RTN4 is named in the same sentence as 179 diseases in open-access papers, as found by Europe PMC text mining. Sharing a sentence is not in itself a finding about the gene and the disease. The quoted sentences say what the papers report.
Stroke (49 papers, 2011 to 2026). Sudden impairment of blood flow to a part of the brain due to occlusion or rupture of an artery to the brain. "Furthermore, we found increased expression of the gene encoding neurite branching mediator Rtn4 in iNSC treated brain tissue, which further indicates that iNSCs may foster neural repair mechanisms after stroke." (PMID 28855627, 2017). "RTN4 is also involved in neuronal regeneration, and has been proposed as a potential therapeutic target because of its role in exacerbating damage after experimental stroke." (PMID 24879061, 2014).
multiple sclerosis (17 papers, 2011 to 2025). A progressive autoimmune disorder affecting the central nervous system resulting in demyelination. "Our results are in accordance with other studies, which showed elevated RTN4 levels in the chronic active demyelinating lesions of brain tissues, cerebrospinal fluid, and blood if patients with multiple sclerosis." (PMID 35887886, 2022). "A high expression of the NgR1/TROY/LINGO-1 receptor complex for RTN4 was revealed at the edge of chronic active demyelination lesions in multiple sclerosis (MS) patients in reactive microglia/macrophage and reactive astrocytes compared with controls." (PMID 35887886, 2022). "The CSF concentration of RTN4 was significantly higher in the group with multiple sclerosis than in the controls." (PMID 35887886, 2022). "The increased RTN4 levels were found in brain tissues, cerebrospinal fluid, and blood of patients with multiple sclerosis." (PMID 34830564, 2021). "In agreement with our findings, other studies have also demonstrated the increased RTN4 levels in the chronic active demyelinating lesions of brain tissues, cerebrospinal fluid, and blood patients with multiple sclerosis." (PMID 34830564, 2021). "Although further analysis revealed that this difference between NfL and RTN4 was insignificant, both biomarkers could be valuable in multiple sclerosis." (PMID 35887886, 2022). "However, no studies on Alzheimer’s and Parkinson’s diseases have been reported in which the concentration of RTN4 in cerebrospinal fluid was assessed, and there are a few studies with respect to multiple sclerosis." (PMID 34830564, 2021).
glioma (15 papers, 2008 to 2025). A benign or malignant brain and spinal cord tumor that arises from glial cells (astrocytes, oligodendrocytes, ependymal cells). "Subsequently, we delved into the function of RTN4 in lower‐grade glioma cells by analysing 100 LGG patients and 3 specimens of normal brain tissue from our institution." (PMID 39969103, 2025). "Firstly, despite observing the phenomenon where the RTN4 gene promotes glioma progression, which concurred with the findings of bioinformatics analysis, the precise biological mechanism underlying this process remains elusive." (PMID 39969103, 2025). "In summary, based on data derived from two databases, namely TCGA and CGGA, along with clinical samples, we have identified RTN4 as a potential oncogene in lower‐grade gliomas." (PMID 39969103, 2025). "To further validate the expression of RTN4 in our cohort, we assayed its expression in our clinical samples and discovered that RTN4 was significantly overexpressed in lower‐grade gliomas." (PMID 39969103, 2025). "The preliminary bioinformatics analysis of RTN4 in lower‐grade gliomas has elicited several pertinent inquiries." (PMID 39969103, 2025). "Ultimately, clinical samples' immunohistochemistry revealed that RTN4 was markedly overexpressed in low‐grade gliomas." (PMID 39969103, 2025). "The presence of exon 3 in RTN4 isoforms is associated with reduced cell proliferation, suggesting that PTB-induced cell proliferation in glioma cells is partly mediated by RTN4 splicing." (PMID 37875914, 2023). "RTN4, which promotes tumor proliferation in glioma via Akt signaling pathway, is downregulated in GBM NS." (PMID 36354672, 2022). "For instance, PTBP1 can enhance glioma proliferation and migration by increasing the inclusion of exon 3 in RTN4 mRNA." (PMID 34733320, 2021). "RTN4 and its receptors are highly expressed in glioma tumor cells, indicating that glioma cells may promote tumor proliferation through an autocrine process." (PMID 36354672, 2022). "We found that RTN4 and its receptors are highly expressed in the neoplastic cells of glioma, indicating that glioma cells may promote tumor proliferation through autocrine RTN4 signaling." (PMID 31118022, 2019). "In human glioma cells, depletion of PTB slowed cell proliferation with enhanced inclusion of exon 3 of RTN4, and the overexpression of RTN4 splicing isoform with exon 3 resulted in a similar degree of decreased cell proliferation as the removal of PTB19." (PMID 27897224, 2016). "These genes had varying degrees of glioma-specific splicing and included APPA4, CLTB, DYNC1I2, NF1, RTN4 and TNC." (PMID 18474104, 2008). "Four genes have clearly identified functions in the central nervous system: APPA4 functions in Notch signaling during neural development, cell adhesion and apoptosis; RTN4 is a neurite growth inhibitor; and SNCB, which is upregulated in glial tumors, is thought to regulate phospholipase D2 activity." (PMID 18474104, 2008). "But there was no significant RTN4 expression in different stages of gliomas." (PMID 39969103, 2025).
hepatocellular carcinoma (13 papers, 2016 to 2025). A malignant tumor that arises from hepatocytes. "For example, silencing the NFE2L2 gene increased 5FU sensitization in hepatocellular carcinoma cells, RTN4 knockdown promoted higher cytotoxic events in paclitaxel-treated cancer cells, and RND3 overexpression promoted drug resistance in gastric cell lines." (PMID 36675023, 2023). "Another study shows that an ER-residential protein, reticulon 4B (NOGO-B), was highly expressed in NAFLD-associated hepatocellular carcinoma (HCC) in both mice and human." (PMID 31614437, 2019). "For example, the RTN4 (aka NOGO) gene has been implicated in lung cancer, hepatocellular carcinoma, and cervical cancer and has diverse roles in epithelial-mesenchymal transition, cell adhesion, and migration." (PMID 27788488, 2016). "In summary, qPCR revealed that all reticulon 4 isoforms were expressed in human hepatoma cells as well as in mouse fibroblasts and primary neurons, but at varying levels." (PMID 27786289, 2016).
schizophrenia (13 papers, 2007 to 2023). A major psychotic disorder characterized by abnormalities in the perception or expression of reality. "Altered expression and polymorphisms of the RTN4 (Reticulon 4) gene, which codes for Nogo-A, have been associated with psychiatric disorders like schizophrenia." (PMID 32425837, 2020). "It is localized on chromosome 2p16, a hotspot for schizophrenic candidate genes and Rtn4 polymorphisms have been detected in schizophrenia patients." (PMID 30040841, 2018). "Indeed, single nucleotide polymorphisms located in Grm3 (mGlu3) or Rtn4 (Nogo-A) genes are positively associated with schizophrenia and deletion of either is known to induce related endophenotypes in mice." (PMID 30040841, 2018). "However, two preliminary reports described sex-specific associations between schizophrenia and common variants in the RTN4R gene, as well as its ligand RTN4." (PMID 18043741, 2007). "Some of these genes have been genetically associated with schizophrenia, namely neuroplastin (Nptn/Sdfr1), numb homolog (Drosophila)-like (Numbl), proteolipid protein 1 (Plp1), gamma-aminobutyric acid (GABA) A receptor, α1 (Gabra1), and reticulon 4 (Rtn4/(NogoA)." (PMID 21629445, 2010).
breast cancer (10 papers, 2013 to 2025). A primary or metastatic malignant neoplasm involving the breast. "For example, hsa-miR-200b-3p had the splice variant-specific binding site in one of RTN4 exons, and this RTN4 splice variant became downregulated in breast cancer tissues." (PMID 36688696, 2023). "We also explored RTN4’s interactions, functions, and implications in apoptosis and breast cancer development via predicting protein–protein interactions and enriched networks." (PMID 37511924, 2023). "Axon guidance signalling proteins Paxillin (PXN) and Reticulon4 (RTN4) showed increased abundance, while GIT1, GRB2 and SHRANK2 showed decreased abundance in breast cancer cells after co-culture." (PMID 39232464, 2024). "Overall, we found two novel FTD-COVID-19 comorbid genes, GFAP and RTN4, and five novel FTD-Breast cancer comorbid genes, AKT3, GFAP, ADCYAP1R1, VDAC1, and C4A, in this study." (PMID 37834358, 2023). "The down-regulation of RTN4 expression leads to a decrease in AKT activation, which is an important event related to breast cancer occurrence and metastasis." (PMID 37426199, 2023).
liver fibrosis (10 papers, 2014 to 2025). "RTN4 can regulate liver fibrosis via facilitating the TGFβ/Smad2 signaling pathway in myofibroblasts." (PMID 39972424, 2025). "Previous studies have demonstrated that RTN4 can facilitate hepatocyte proliferation and liver regeneration, suggesting that RTN4 is an important regulator of hepatic fibrosis." (PMID 36925557, 2023). "Accumulating research also reported the importance of RTN4 in tissue repairing and hepatic fibrosis." (PMID 34194321, 2021). "The talk focused on Nogo-B (Reticulon 4B), a novel regulator of liver fibrosis and portal hypertension." (PMID 24484528, 2014).
Alzheimer disease (9 papers, 2014 to 2024). A progressive, neurodegenerative disease characterized by loss of function and death of nerve cells in several areas of the brain leading to loss of cognitive function such as memory and language. "We validated a circRNA in RTN4, a gene inhibiting axonal sprouting and modulating Alzheimer’s disease progression in a mouse model and one of two predicted circRNAs in HOMER1, a gene that is involved in synaptic activity and various neurological disorders." (PMID 28842720, 2017). "In this work, we focused on knowledge cliffs next to some of the most-established interactions such as BACE1-APP and found four “potential new candidates”, namely TP53INP2, RTN4, F2RL3, and FBXO2, presumably new targets for Alzheimer’s disease as guided by the knowledge cliff concept." (PMID 26346705, 2015).
demyelinating disease (7 papers, 2015 to 2025). A broad group of disorders that affect the myelin sheaths that cover the neurons. "RTN4 (also known as Nogo) is a myelin-associated protein that inhibits axon outgrowth in the central nervous system, and has exhibited great potential as a therapeutic target for treating demyelinating diseases and spinal cord injuries." (PMID 36835443, 2023). "More specifically, RTN4 is related to Demyelinating Disease and KAZALD1 is related to Lobar Holoprosencephaly." (PMID 29671403, 2018).
glioblastoma (7 papers, 2016 to 2024). The most malignant astrocytic tumor (WHO grade IV). "Interestingly, we found the GJB2 (also known as connexin 26): RTN4 (also known as NOGO) pair in the CTmvp signature, with both genes being indicative of poor prognosis in glioblastoma." (PMID 33927352, 2021).
Cognitive impairment (6 papers, 2014 to 2024). Abnormal cognition is characterized by deficits in thinking, reasoning, or remembering. "Moreover, it seems to be the approach measuring the level of RTN4 protein not only in various neurological diseases manifested by cognitive impairment but also in different stages of advancement of cognitive decline." (PMID 34830564, 2021). "In our study, we assessed the concentrations of RTN-4 in CSF patients with two of the most common neurodegenerative diseases, such as AD and PD, subjects with the neurological disease in which cognitive impairment develops (MS), and control group (i.e., individuals without cognitive decline)." (PMID 34830564, 2021).
brain tumors (5 papers, 2016 to 2022). "The influence of isoform A of reticulon-4 (Nogo-A), also known as neurite outgrowth inhibitor, on primary brain tumor development was reported." (PMID 29861852, 2018).
cardiac hypertrophy (5 papers, 2016 to 2025). "The decreased RTN4 isoforms (RTN4B2 and RTN4C) in the submucosa/wall may be related to the dysregulation of neural processes detected in pathway analysis and the histologic feature of neural hypertrophy in the intestinal wall of our CD patient samples." (PMID 38791146, 2024).
colorectal cancer (5 papers, 2021 to 2025). A primary or metastatic malignant neoplasm that affects the colon or rectum. "Recently, numerous studies conducted domestically and internationally have implicated RTN4 in the pathogenesis of gastric cancer, colorectal cancer, HCC and prostate cancer." (PMID 39969103, 2025). "RTN4 exhibited a profound association with the pathogenesis of gastric cancer, colorectal cancer, HCC, prostate cancer and numerous other malignancies." (PMID 39969103, 2025). "Recently, acrylamide probes have been shown to covalently modify specific cysteine residue 1101 (Cys1101) on RTN4 by LC-MS/MS assay, thereby impairing colorectal cancer cell growth." (PMID 40683874, 2025). "RNA interference-mediated knockdown of RTN4 has been shown to inhibit cell growth of human colorectal cancer cells." (PMID 35174178, 2021). "Furthermore, RTN4 plays a pivotal role in the proliferative capacity of colorectal cancer cells." (PMID 39969103, 2025).